LGALS3 (galectin 3)
Diseases named in the same sentence as LGALS3 in open-access papers (continued):
Sharing a sentence is not in itself a finding about the gene and the disease.
papillary thyroid carcinoma (continued). "In a similar fashion, LGALS3 expression increases in papillary carcinoma tissues, and is similar in follicular carcinoma and adenoma tissues; indeed, our measurement of LGALS3 transcript expression in blood revealed the same tendency in that it was marginally higher in papillary carcinomas." (PMID 30781659, 2019). "In addition, LGALS3 expression in the blood of those with papillary thyroid carcinomas was higher than in that of those with follicular thyroid carcinomas." (PMID 30781659, 2019). "Taken together these data suggested that cytoplasmic galectin-3 staining could be a reliable, easy, and cheap marker for presurgical diagnosis of follicular carcinomas and an even more suitable one for papillary carcinomas." (PMID 23658855, 2010). "According to recent research, several diagnostic and prognostic markers have been proposed in improving the diagnostic accuracy of papillary thyroid cancer such as Cytokeratin-19 (CK-19), HBME-1, Galectin-3, CD44, CD56, E-cadherin, c-erbB-2, p21cip1, p27kip1, and p16ink4a." (PMID 21052476, 2010). "To examine whether the delay between fine-needle aspiration and galectin-3 immunodetection could be longer than 48 h, we tested the human papillary thyroid carcinoma BCPAP cell line for galectin-3 after incubation in CytoLyt for different times (4 h–7 days)." (PMID 16251880, 2005). "CD56 and Galectin-3 could not differentiate between follicular variant of papillary carcinoma and follicular carcinoma." (PMID 26503236, 2015). "Combined statistical validation of HBME-1, galectin-3, and BRAF V600E co-expression in differentiating among papillary thyroid carcinoma, papillary thyroid hyperplasia, follicular adenoma, and follicular carcinoma." (PMID 34934597, 2021). "Correlation analysis of the expressions of has-miR-200a-5p to TPO, CD56, Galectin-3, MC, CK19 and B-raf in papillary thyroid carcinoma." (PMID 30005075, 2018). "The expressive levels of miR-200a-5p, TPO, CD56, Galectin-3, MC, CK19 and B-raf in benign thyroid tumors with papillary hyperplasia and papillary thyroid carcinoma." (PMID 30005075, 2018). "Simultaneous immunopositivity for HBME-1 and Galectin 3, and HBME-1 and CK19 in the diagnosis of differentiated thyroid carcinoma have sensitivities of 85,9 %, and 86.4 % respectively, and specificities of 100 % for both combinations." (PMID 26503236, 2015). "Quantitative RT–PCR was performed (ADM3, HGD1, LGALS3, PLAB, TFF3, TG) in the needle wash-out of 156 FNAB of follicular adenoma (FA), adenomatous nodules, follicular and papillary thyroid cancers (TC) and normal thyroid tissues (NT)." (PMID 22223087, 2012). "In this study, we found that CK-19, Galectin-3, CD-44, and HBME1 were highly expressed in papillary carcinomas, a finding that is in agreement with other data reported in the literature." (PMID 21052476, 2010). "As demonstrated, the association of positivity for CK-19, Gal-3 and HBME-1 in IHC assays and the preoperative expression of galectin-3 in ICC samples proved to be highly accurate tests in the distinction between benign and well-differentiated thyroid carcinoma." (PMID 22888980, 2012). "Galectin-3 positive rate in these four groups was 52.58% (nodular goiter), 48.15% (follicular adenoma), 97.17% (papillary thyroid carcinoma without lymphatic metastasis) and 96.37% (papillary thyroid carcinoma with lymphatic metastasis), respectively." (PMID 22188859, 2011). "As expected, almost all the thyroid papillary carcinomas tested as controls showed coexpression of galectin-3, HBME-1, c-met protein and cyclin D1 (data not shown)." (PMID 15292926, 2004). "In this context, the possibility that MFT–or at least some of its foci in a given case–may precede the development of papillary carcinoma is tantalizing and may be further supported by partial alteration of HBME-1, cytokeratin 19, Galectin-3, and CD56 expression patterns." (PMID 35819567, 2022).
papillary thyroid carcinoma (continued). "Best discriminatory combinations of markers for papillary carcinoma from follicular adenoma, and non-neoplastic lesions were CD56 with Galectin 3, and CK19 with Galectin 3, respectively." (PMID 26503236, 2015).
Sepsis (35 papers, 2013 to 2026). Sepsis is defined as life-threatening organ dysfunction caused by a dysregulated host response to infection. "Galectin-3 (Gal-3) is a damage-associated molecular pattern (DAMP) protein that amplifies inflammatory cascades during sepsis and represents a potential therapeutic target." (PMID 41930343, 2026). "The values of galectin-3 were significantly increased in the group of patients with sepsis caused by peritonitis and pancreatitis compared to the control population of patients who had only trauma (p < 0.05)." (PMID 38152329, 2023). "The outcome of this study, with use of galectin-3 deficient mice, shows that galectin-3 plays the role of an alarmin in Francisella infection induced sepsis development." (PMID 23527230, 2013). "In Toto, our findings indicate that galectin-3 plays a pathogenic role as an alarmin to exacerbate the inflammatory response during pulmonary infection with Francisella and contributes to sepsis development." (PMID 23527230, 2013). "Genes such as MYC (a transcription factor, TF), SELL, and LGALS3 (associated with cold shock domain-containing protein A) may act as upstream regulators or potential therapeutic targets in the context of glycosylation dysfunction related to sepsis." (PMID 40672940, 2025). "In murine model of sepsis induced by Francisella novicida, Galectin-3 deficient mice showed reduced inflammatory response and neutrophil accumulation, while in WT mice increased extracellular accumulation of Galectin-3 was followed by hyperinflammatory response." (PMID 32455781, 2020). "Galectin-3 promotes caspase-4/11-mediated pyroptosis in macrophages during sepsis and drives LLPS via its NTD interaction." (PMID 40624022, 2025). "The expression of LGALS3 promotes myocardial ischemia-reperfusion injury, induces inflammation and exacerbates sepsis." (PMID 39823512, 2025). "Not all targets in the sepsis pathway are related to glycocalyx, and there are 6 targets (SI, ROCK1, TLR4, VEGFA, HPSE, and LGALS3) of active ingredients not only related to glycocalyx, but also involved in the sepsis pathway." (PMID 36062176, 2022). "Among them, BCHE, AKT1, and IL2 are involved in the sepsis pathway, and LGALS3 is involved in both the sepsis and glycocalyx pathways." (PMID 36062176, 2022). "The combination of presepsin with PCT, galectin-3, and soluble suppression of tumorigenicity-2 showed better performance in predicting mortality than the single use of presepsin for sepsis patients." (PMID 34983420, 2022). "Plasma ALT, AST, and galectin-3 concentrations in the sepsis groups at either 12 or 24 h post-CLP were significantly higher than those in the NC and SH groups." (PMID 32290120, 2020). "Conversely, galectin-3 and -9 have been proposed to act as alarmins (or DAMPs) that amplify inflammatory responses during sepsis and several types of infection." (PMID 32632085, 2020). "Our results are novel with respect to combined use of PCT, presepsin, galectin-3, and sST2 as markers of sepsis per se and organ dysfunction." (PMID 28271449, 2017). "This study demonstrated a possible prognostic utility of PCT, presepsin, galectin-3, and sST2 in sepsis." (PMID 28271449, 2017). "In this study we show that galectin-3, a mammalian β-galactoside binding lectin acts as a novel alarmin in development of sepsis during pulmonary infection with F. novicida." (PMID 23527230, 2013). "The reduced number of leukocytes in infected galectin-3−/− animals in this study indicates that this lectin likely plays a role in recruitment of these cells in sepsis." (PMID 23527230, 2013). "In the current study we investigated the role of galectin-3, a mammalian β-galactoside binding lectin, as an alarmin in sepsis development during F. novicida infection." (PMID 23527230, 2013). "Collectively, these findings suggest that galectin-3 functions as an alarmin by augmenting the inflammatory response in sepsis development during pulmonary F. novicida infection." (PMID 23527230, 2013).
Sepsis (continued). "Nonetheless, this augmentation of Francisella infection-induced myeloid cell activation by galectin-3 likely has implications in exacerbation of inflammation culminating in sepsis development during this infection." (PMID 23527230, 2013). "Galectin-3, a β-galactoside-binding lectin involved in inflammation and fibrosis, and presepsin, an established biomarker for bacterial infection and sepsis, have emerged as potential biomarkers for improving diagnostic and prognostic accuracy in autoinflammatory diseases." (PMID 41008774, 2025). "Our findings are in line with the previous findings and new sepsis definition, and galectin-3 and sST2 may have reflected circulatory abnormalities in this study population." (PMID 28271449, 2017). "In this scenario a combinatorial approach using blockade of galectin-3 and galectin-9 along with antibiotics could potentially treat Francisella infection induced sepsis." (PMID 25898318, 2015). "In addition, levels of several inflammatory cytokines (TNF-α, IL-10, IL-1β), described as markers of sepsis, were reduced in galectin-3−/− mice." (PMID 23527230, 2013). "Results from the current study showed that F.n. infected galectin-3−/− animals exhibited a reduction in the levels of sepsis mediators such as vascular injury markers thrombopoietin, fibrinogen, as well as acute phase protein CRP and inflammatory cytokines such as TNF-α, IL-6 and IL-1." (PMID 23527230, 2013). "We hypothesized that, similar to the function of alarmins, increased expression and extracellular localization of galectin-3 may be contributing to the hyperinflammatory response culminating in sepsis during lethal Francisella infection." (PMID 23527230, 2013). "Galectin-3 thus may represent a potential target for treatment of sepsis during this infection." (PMID 23527230, 2013). "Thus, a combinatorial approach using blockage of galectin-3 along with antibiotics could prove to be a successful therapy for treating Francisella infection induced sepsis." (PMID 23527230, 2013). "Very recently, elevated levels of FCN3, together with galectin-3, have also been found in sera of patients with AKI, following complicated sepsis and correlated with the severity of renal damage." (PMID 40427671, 2025). "The sepsis groups with L-NIL administration also showed higher plasma ALT, AST, and galectin-3 levels than the control groups." (PMID 32290120, 2020). "Similarly, a combination of several sepsis-related biomarkers (PCT, presepsin, galectin-3, and soluble suppression of tumorigenicity 2) was found to have better prognostic value than PCT alone." (PMID 32503670, 2020).
autoimmune disease (34 papers, 2016 to 2026). A disorder resulting from loss of function or tissue destruction of an organ or multiple organs, arising from humoral or cellular immune responses of the individual to their own tissue constituents. "Galectin-3, a β-galactoside–binding lectin, has been implicated in several inflammatory and autoimmune diseases." (PMID 41477833, 2026). "Galectin-3 is a β-galactoside binding protein and is associated with neutrophil functions as well as involved in mediating autoimmune disorders." (PMID 37298447, 2023). "LGALS3 encodes for galectin-3, which has been implicated in various autoimmune diseases through modulation of T cell functions." (PMID 36609529, 2023). "Similar studies suggested association of high serum galectin-3 levels with inflammatory disorders and autoimmune diseases, including rheumatic diseases." (PMID 33076422, 2020). "In autoimmune diseases, Galectin-3 often functions as a proinflammatory amplifier, including in experimental autoimmune encephalomyelitis and rheumatoid arthritis." (PMID 41477833, 2026). "Recent studies have revealed that Galectin-3 plays a pivotal role in the pathogenesis of various autoimmune diseases by modulating immune cell functions and amplifying inflammatory responses, which collectively promote disease progression." (PMID 41477833, 2026). "Galectin-3 has been related to type 1 diabetes, an autoimmune disease characterized by pancreatic β-cell destruction mediated by autoreactive T lymphocytes." (PMID 39483979, 2024). "Galectin-3 (Gal-3), a unique chimera-type galectin member, exerts diverse immunoregulatory effects in T-cell-mediated inflammatory processes, autoimmune diseases, and tumor progression." (PMID 38172822, 2024). "The pivotal role of galectin-3 in autoimmune diseases and neutrophil phagocytosis of Candida infection implies that Candida infection and SjS share a common pathological pathway." (PMID 35127751, 2021). "Galectin 3 appears to be a proinflammatory molecule in several inflammatory and autoimmune diseases." (PMID 32117058, 2020). "Galectin-3 is highly expressed in tissues affected by several autoimmune diseases, such as systemic lupus erythematosus, polymyositis, dermatomyositis, rheumatoid arthritis, Behcet's disease, systemic sclerosis, and Crohn's disease." (PMID 28593065, 2017). "Further studies will need to explore the exact mechanism behind the function of galectin-3 in IgG4-RD and other autoimmune diseases." (PMID 28593065, 2017). "Galectin-3 (Gal-3) has diverse roles in inflammatory and autoimmune diseases." (PMID 34803672, 2021). "Aims/Hypothesis: Galectin 3 appears to play a proinflammatory role in several inflammatory and autoimmune diseases." (PMID 32117058, 2020). "Interestingly, whilst galectin-1 can inhibit autoimmune diseases, the research focus on galectin-3's potential therapeutic use is in large focusing on inhibiting galectin-3." (PMID 29950926, 2018). "In patients with autoimmune disease, even if lacrimal gland function is not impaired, secretory mucin disorders may occur because of a reduction in secreted-type mucin caused by a decrease in goblet cells, and destruction of membrane-type mucin and galectin-3 due to inflammation." (PMID 40095328, 2025).
idiopathic pulmonary fibrosis (34 papers, 2020 to 2026). Idiopathic pulmonary fibrosis (IPF) is a nonneoplastic pulmonary disease that is characterized by the formation of scar tissue within the lungs in the absence of any known cause. "What is important is that galectin-3 plays a significant role in the fibrosis in IgG4-RD, as well as in an idiopathic pulmonary fibrosis (IPF)." (PMID 35145508, 2021).
rheumatoid arthritis (33 papers, 2013 to 2026). A chronic, systemic autoimmune disorder characterized by inflammation in the synovial membranes and articular surfaces. "The LGALS3 +292 C allele carries proline and was associated with lower serum GAL-3 levels in rheumatoid arthritis (RA), since the proline at GAL-3 residue 98 is located in a critical protein transport determination region." (PMID 27603703, 2016). "Reciprocal regulation of galectin-1 and galectin-3 has also been observed in sera from patients with rheumatoid arthritis undergoing various treatments, suggesting possible compensatory mechanisms." (PMID 33583770, 2021). "Our study showed that galectin-3 has a high diagnostic sensitivity, specificity, PPV, and diagnostic accuracy in rheumatoid arthritis and systemic sclerosis patients." (PMID 33076422, 2020). "The results of this study have shown increased serum concentration of galectin-3 in all studied rheumatic diseases: rheumatoid arthritis, systemic sclerosis, and systemic lupus erythematosus in comparison to the healthy subjects." (PMID 33076422, 2020). "Elevations in synovial fluid galectin-3 have been observed in rheumatoid arthritis, juvenile idiopathic arthritis and experimental inflammatory arthritis in animal models, whereas galectin-1 is thought to be protective." (PMID 30525048, 2018). "Decreased galectin-1 and increased galectin-3 synovial fluid concentrations have been reported in human patients with OA, juvenile idiopathic arthritis and rheumatoid arthritis." (PMID 29096716, 2017). "Galectin-1 and galectin-3 are proposed to be important intra-articular modulators of inflammation in both osteoarthritis and rheumatoid arthritis." (PMID 29096716, 2017). "Galectin-1 and galectin-3 have both been previously identified in the proteome of fibroblast-like synoviocytes from patients with rheumatoid arthritis." (PMID 29096716, 2017). "A previous report revealed that TNF-α reduced galectin-3 protein expression as measured by flow cytometry in human OA and rheumatoid arthritis synovial fibroblasts 18 hours following exposure to TNF-α." (PMID 29096716, 2017). "The first signal, led by rs140884539-C (P-value = 7.05×10-08, beta = 0.59), was in strong linkage disequilibrium with variants associated with predisposition to rheumatoid arthritis, decrease in dopamine, increased levels of GCH1 transcript, dopamine metabolites, and galectin-3." (PMID 41667488, 2026). "Galectin-3 and galectin-3 binding protein, LGALS3BP were elevated in rheumatoid synovial fluid, while galectin-3 was elevated in sera of rheumatoid arthritis patients." (PMID 23826184, 2013). "The present observation of a strong and independent relationship between elevated plasma Galectin-3 and increasing SVR was also documented recently, but in a very different cohort of patients with low-grade systemic inflammation (long-standing rheumatoid arthritis)." (PMID 32392260, 2020). "Galectin-3 was increased in pre-rheumatoid arthritis (RA) (4.6 μg/l, interquartile range (IQR) 3.8–5.5) versus non-RA (4.0 μg/l, IQR 3.1–4.9; p = 0.03) and controls (3.8 μg/l, IQR 3.0–4.8; p = 0.009)." (PMID 28446218, 2017).
metabolic syndrome (32 papers, 2015 to 2026). A cluster of metabolic risk factors for CARDIOVASCULAR DISEASES and TYPE 2 DIABETES MELLITUS. "Recent studies have shown that circulating concentrations of galectin-3 are positively associated with several cardiometabolic disorders, including dyslipidemia." (PMID 35208606, 2022). "Therefore, determination of galectin-3 blood levels, as a marker of fibrosis, may be used for indirect assessment of fibrosis severity and the risk of AF in patients, especially those with metabolic syndrome." (PMID 35208606, 2022). "Consistent with our data, previous data have reported that galectin-3 levels were negatively associated with HDL-C levels in the general population and in patients with MI6, suggesting that galectin-3 may be a link between dyslipidemia and inflammation." (PMID 38195853, 2024). "The patients had dyslipidemia, mild increases in HOMA-IR, circulating creatinine, inflammatory biomarkers (hs-CRP, TNF-alpha, IL-6), and indicators of fibrosis (galectin-3 and sST2)." (PMID 40299414, 2025).